GATA5 (GATA binding protein 5)
Description:
Transcription factor required during cardiovascular development. Plays an important role in the transcriptional program(s) that underlies smooth muscle cell diversity (By similarity). Binds to the functionally important CEF-1 nuclear protein binding site in the cardiac-specific slow/cardiac troponin C transcriptional enhancer.
Synonyms: bB379O24.1; GATAS; CHTD5
Tractability: No criterion of Open Targets' tractability assessment is met for any kind of drug.
Gene: Protein-coding gene on chromosome 20 (62,463,481 to 62,476,040, reverse strand). Ensembl gene ENSG00000130700.
Subcellular location: Nucleus
Subcellular location (Human Protein Atlas): Nucleoplasm; Cytosol
Pathways (Reactome):
Hemostasis: Factors involved in megakaryocyte development and platelet production
Gene Ontology:
Molecular function: DNA-binding transcription factor activity; protein binding; sequence-specific double-stranded DNA binding; transcription cis-regulatory region binding; DNA-binding transcription factor activity, RNA polymerase II-specific; RNA polymerase II cis-regulatory region sequence-specific DNA binding; cis-regulatory region sequence-specific DNA binding; DNA binding; sequence-specific DNA binding; zinc ion binding
Biological process: aortic valve morphogenesis; intestinal epithelial cell differentiation; positive regulation of transcription by RNA polymerase II; cardiac muscle tissue development; cell fate commitment; endocardial cushion fusion; heart induction; negative regulation of gene expression; negative regulation of transcription by RNA polymerase II; positive regulation of cardiac endothelial to mesenchymal transition; positive regulation of gene expression; positive regulation of Notch signaling pathway; anatomical structure morphogenesis; cell differentiation; heart development; negative regulation of cardiac muscle hypertrophy; positive regulation of DNA-templated transcription; regulation of DNA-templated transcription; regulation of transcription by RNA polymerase II; tissue development
Cellular component: nucleus; chromatin; nucleoplasm
Genetic constraint (gnomAD): Loss-of-function variants: 27 observed, 22.79 expected, observed/expected ratio (o/e) 1.18, 90% interval 0.87 to 1.63. The synonymous counts are far from expectation, so gnomAD's model fits this gene poorly and the ratio says little. Missense variants: 612 observed, 432.84 expected, observed/expected ratio (o/e) 1.41, 90% interval 1.32 to 1.51. Synonymous variants: 306 observed, 198.59 expected, observed/expected ratio (o/e) 1.54, 90% interval 1.4 to 1.69.
Homologues: Orthologues: chimpanzee GATA5 (99% identical), macaque GATA5 (95% identical), pig GATA5 (79% identical), dog GATA5 (79% identical), rat Gata5 (78% identical), mouse Gata5 (77% identical), zebrafish gata5 (54% identical), guinea pig GATA5 (51% identical), tropical clawed frog gata5 (50% identical), Drosophila melanogaster pnr (36% identical), Caenorhabditis elegans elt-2 (16% identical), Caenorhabditis elegans elt-4 (9% identical). Paralogues in human: GATA4 (47% identical), GATA6 (46% identical), GATA2 (35% identical), GATA3 (33% identical), GATA1 (31% identical), TRPS1 (22% identical), ZGLP1 (8% identical).
Diseases named in the same sentence as GATA5 in open-access papers:
GATA5 is named in the same sentence as 87 diseases in open-access papers, as found by Europe PMC text mining. Sharing a sentence is not in itself a finding about the gene and the disease. The quoted sentences say what the papers report.
Hypertension (11 papers, 2015 to 2025). The presence of chronic increased pressure in the systemic arterial system. "In this study, GATA5 was extracted as one of the hypertension-associated genes in the atrium (fold change = 1.53, p = 0.04)." (PMID 38451262, 2024). "Previous studies have shown that GATA5 plays an important role in CVDs as GATA5 loss-of-function mutations are closely related to congenital heart disease, atrial fibrillation, hypertension." (PMID 33684162, 2021). "Consistent with a role in human hypertension, we report genetic association of variants at the GATA5 locus with hypertension traits in two large independent cohorts." (PMID 26617239, 2015). "Consistent with a possible role in human hypertension, we find genetic association of variants within the GATA5 locus with prescription of anti-hypertensive medication in two large independent cohorts." (PMID 26617239, 2015). "In mice, loss of GATA5 leads to a hypertensive phenotype that reproduces several of the features of human hypertension, including vascular dysfunction, salt sensitivity and target-organ damage." (PMID 26617239, 2015). "GATA5 was associated with endothelial dysfunction and hypertension." (PMID 40780200, 2025). "Together these data suggest that GATA5 might be a susceptibility gene for human hypertension." (PMID 26617239, 2015). "Thus, GATA5 may be a susceptibility locus for hypertension and possibly other endothelial-dependent human disorders." (PMID 26617239, 2015). "GATA4 expression also tended to be higher in the hypertension group, although its fold change was lower than that of GATA5 (fold change = 1.33, p = 0.06)." (PMID 38451262, 2024). "In supporting of this, literature argued that endothelial Sirt6 plays a regulatory role in preventing hypertension by aiming at GATA5 (GATA binding protein 5) signaling pathway." (PMID 37497437, 2023). "GATA5 is responsible for activation of several intestinal genes, and its inactivation in mice results in vascular endothelial dysfunction and hypertension." (PMID 36883013, 2023). "At the same time, SIRT6 activity prevents hypertension and its renal complications by maintaining endothelial homeostasis through the induction of GATA-binding protein 5 (GATA5) via NK3 homeobox 2 (Nkx3.2) transcription inhibition." (PMID 35328633, 2022). "Mechanistically, SIRT6 prevented hypertension by inducing the expression of GATA-binding protein 5 (GATA5) through inhibiting the expression of NK3 homeobox 2, a transcriptional repressor, by deacetylating histone H3 lysine 9 in its promoter." (PMID 34220553, 2021). "Here, the authors identify the transcription factor GATA5 as a novel regulator of blood pressure and potential genetic determinant of human hypertension and describe a unique mouse model for research of salt-sensitive hypertension." (PMID 26617239, 2015). "Altogether, these results indicate that GATA5 regulates multiple pathways essential for endothelial homeostasis that can directly contribute to the onset and maintenance of hypertension." (PMID 26617239, 2015). "Gata5-null mice represent a unique model of hypertension that reproduces several features of human essential hypertension." (PMID 26617239, 2015). "The Gata5-null mice exhibit several essential features of low-renin hypertension: significant increase in BP, low-renin plasma activity, salt sensitivity and severe renal alterations." (PMID 26617239, 2015). "Our results unveil an unsuspected link between GATA5 and a prominent human condition, and provide a new animal model for hypertension." (PMID 26617239, 2015). "GATA5 is expressed in microvascular endothelial cells and its genetic inactivation in mice (Gata5-null) leads to vascular endothelial dysfunction and hypertension." (PMID 26617239, 2015). "The Gata5-null mice represent, therefore, a new model of systemic hypertension that reproduces several of the features found in hypertensive patients." (PMID 26617239, 2015).
Hypertension (continued). "In addition, Sirt6 prevented the complications of pathological hypertension by maintaining endothelial function through the epigenetic regulation of Nkx3.2‐mediated GATA5 signalling." (PMID 35842903, 2022). "GATA binding protein 5 (GATA5) is a member of GATA family and plays an important role in CVDs as GATA5 loss-of-function mutations are closely related to congenital heart disease, atrial fibrillation, hypertension." (PMID 33684162, 2021). "We report that GATA5 is present in microvascular endothelial cells and that its absence in mice leads to increased BP, endothelial dysfunction and age-dependent end-organ damage, which are all features of human hypertension." (PMID 26617239, 2015). "Finally, the Gata5-null mice provide a new tool for addressing gene–gene and gene–environment interactions in the onset and progression of hypertension and other diseases of the endothelium." (PMID 26617239, 2015). "Similar to patients with low-renin hypertension, Gata5-null mice respond well to thiazide therapy and may be a useful model to further analyse the pathophysiology and progression of disease." (PMID 26617239, 2015). "We tested whether the evolution of hypertension in Gata5-null mice follows the natural history of human hypertension." (PMID 26617239, 2015). "Association between GATA5 sequence variants and use of hypertension medication in two large independent studies suggest that GATA5 might be relevant to human hypertension." (PMID 26617239, 2015). "Additionally, functional dysregulation of GATA5 could result in the development of hypertension, arrhythmia, and other human diseases through different signaling pathways." (PMID 40076735, 2025). "Finally, to confirm that endothelial dysfunction was inherent to loss of GATA5, not secondary to hypertension, we treated Gata5-null mice and their controls with hydralazine, a widely used vascular smooth muscle cell relaxant." (PMID 26617239, 2015). "Together, these data suggest that lack of GATA5 from endothelial cells promotes glomerular lesions and renal inflammation likely reflecting altered renal endothelial cross-talk with other cell types, which can contribute to hypertension development." (PMID 26617239, 2015).
gastric cancer (6 papers, 2010 to 2024). A primary or metastatic malignant neoplasm involving the stomach. "For colorectal and gastric cancer, GATA5 is silenced, and overexpression of GATA5 activates downstream antitumor target genes and can be used as a potentially valid noninvasive biomarker." (PMID 35565203, 2022). "Promoter methylation of the GATA5 gene has been involved in gastric cancer biology." (PMID 38435839, 2024). "Specifically, the methylation of GATA4 and GATA5 has been frequently observed in gastric cancer, which suggests that these genes may be tumor suppressors." (PMID 27598141, 2016). "In colorectal and gastric cancer cell lines, GATA4 and GATA5 genes and their target genes including DAB2 promoter were found to be hypermethylated, suggesting epigenetic silencing may be responsible for loss of DAB2 protein expression in these cell lines." (PMID 20525238, 2010).
lung carcinoma (6 papers, 2011 to 2025). "Our results, together with the observations in lung cancers suggest that high levels of GATA5 DNA methylation could be linked to molecular pathways involving DNA damage and repair due to exposure to DNA damaging agents such as the carcinogens in tobacco." (PMID 22028801, 2011). "GATA1, GATA4 and GATA5 were exceptionally downregulated in lung cancer cell lines, including SCLC and NSCLC." (PMID 34093794, 2021). "GATA5 transcriptionally activated ARHGAP9, and restoration of ARHGAP9 expression significantly inhibited proliferation, migration, and invasion of lung-cancer cells, revealing the GATA5-ARHGAP9 axis as a potential therapeutic target." (PMID 41514651, 2025). "Promoter methylation of eight lung cancer-specific genes (CDO1, TAC1, SOX17, HOXA7, HOXA9, GATA4, GATA5, and PAX5) was detected using nanoparticle-based DNA extraction (MOB) followed by qMSP." (PMID 32138766, 2020). "The aberrant expression or DNA modification of GATA-2, GATA-4, GATA-5, and GATA-6 was found in lung cancer, but GATA-1 gene expression is seldom reported in LADC." (PMID 29100282, 2017). "This conclusion is also in agreement with the observations that GATA5 DNA methylation is a common marker for both types of esophageal cancers, EAC and esophageal squamous cell carcinoma (ESCC), as well as for three different types of lung cancers that each have distinct cells of origin." (PMID 22028801, 2011).
breast carcinoma (5 papers, 2006 to 2025). "Additionally, we found that the transcription factors encoding GATA-4 and GATA-5 genes, whose promoter DNA is hypermethylated, were also re-expressed in both colon and breast cancer cells (unpublished data)." (PMID 16596166, 2006). "However, GATA5 has not been widely investigated in breast cancer." (PMID 30872657, 2019). "Tumor cell lines (renal, bladder, prostate and breast cancer) revealed distinct CGI methylation patterns for GATA3 and GATA5 methylation but showed no obvious overall correlation between the epi-alterations." (PMID 24549248, 2014).
congenital heart disease (5 papers, 2017 to 2025). A heart disease that is present at birth. "Our previous researches have found that five mutation sites in GATA4 gene promoter, two mutation sites in GATA5 gene promoter, and two mutation sites in GATA6 gene promoter were associated with congenital heart disease." (PMID 33684162, 2021). "Therefore, the expression and the role of GATA5 partially overlap that of GATA4 and GATA6 during development, making it an important molecular factor for different congenital heart diseases." (PMID 40076735, 2025). "The conserved zinc finger transcription factor proteins, which include GATA binding protein 5 (GATA5) and GATA binding protein (GATA6) play important roles in embryonic development and their inactivation may result in congenital heart defects (CHDs)." (PMID 40076735, 2025).
hepatocellular carcinoma (5 papers, 2019 to 2022). A malignant tumor that arises from hepatocytes. "For example, depletion of GATA binding protein 5 (GATA5) expression causes the proliferation and colony formation in hepatocellular carcinoma cells, but upregulated GATA5 suppresses the growth and metastasis of cholangiocarcinoma cells." (PMID 35358005, 2022). "Loss of GATA5 is involved in the development of hepatocellular carcinoma." (PMID 35565203, 2022). "In hepatocellular carcinoma, it has been reported that GATA5 expression is lower due to aberrant hypermethylation, and the level of GATA5 mRNA is significantly associated with patients’ overall survival." (PMID 35565203, 2022). "Furthermore, GATA5 is involved in suppressing expression of the reprogramming genes and stemness markers in hepatocellular carcinoma cells." (PMID 36685890, 2022). "For instance, GATA5 overexpression restrained the growth and metastasis of cholangiocarcinoma cells, while GATA5 silencing enhanced cell proliferation and colony formation in hepatocellular carcinoma cells." (PMID 35358005, 2022). "Explore the effect of GATA5 expression on Paclitaxel inhibiting growth of hepatocellular carcinoma (HCC)cells." (PMID 32779438, 2020). "Evidence indicated that GATA5 may suppress hepatocellular carcinoma (HCC) cell malignant transformation, but the mechanism of how GATA5 affects cancer cell reprogramming to inhibit HCC malignant behaviour is still unclear." (PMID 30672133, 2019).
aortic stenosis (4 papers, 2012 to 2025). Aortic valve stenosis is a aortic valve disease caused by the incomplete opening of the aortic valve. "Subsequently, genetic variations in human GATA5 were associated with several CHDs, including aortic stenosis, pulmonary stenosis, double outlet right ventricle, tetralogy of Fallot (TOF), bicuspid aortic valve, ventricular septal defect (VSD), and atrial septal defect (ASD)." (PMID 40076735, 2025). "Hemodynamic evaluation of Alk2/Gata5-Cre mutant and age/sex-matched control mice demonstrated an increased velocity gradient across the aortic valve of 6 mutant mice consistent with aortic stenosis." (PMID 22536403, 2012). "In Gata4+/− mice, a small number of heterozygote mutants were double outlet right ventricle (DORV), and in Gata4+/−;Gata5+/− double heterozygote mutants, almost all embryos were DORV, some of which had further aortic stenosis." (PMID 32843646, 2020). "GATA5 was previously shown to be a strong partner of NFATC1 and its recent inactivation in mice did show that the embryos develop aortic stenosis one of the most frequent valve abnormalities." (PMID 23226213, 2012).
cholangiocarcinoma (4 papers, 2022 to 2023). A carcinoma that arises from the intrahepatic biliary tree (intrahepatic cholangiocarcinoma) or from the junction, or adjacent to the junction, of the right and left hepatic ducts (hilar cholangiocarcinoma). "Take cholangiocarcinoma as an instance, GATA5 upregulation was reported to suppress the growth, migration and invasion of cholangiocarcinoma cells." (PMID 35040754, 2022). "In addition, GATA5 suppressed cholangiocarcinoma cell growth and metastasis via the Wnt/β-catenin pathway." (PMID 36961416, 2023). "In addition, GATA5 overexpression suppressed cholangiocarcinoma cells’ proliferation and metastasis through regulating the Wnt/β-catenin signaling pathway." (PMID 35565203, 2022).
colon carcinoma (4 papers, 2006 to 2025). "A previous study reported that inhibition of LSD1 with polyamine analogs not only increased global levels of H3K4 methylation, but also H3K9ac, an epigenetic mark at active promoters, at the promoters of SFRP1, SFRP5, SFRP5 and GATA5 in human colon carcinoma cells." (PMID 38971831, 2024). "They reported that the inhibition of LSD1 in human colon carcinoma cells by biguanide and bisguanidine polyamine analogues resulted in a re-expression of aberrantly silenced genes, including SFRP1, SFRP4, SFRP5, and GATA5." (PMID 23922913, 2013).
colorectal cancer (4 papers, 2011 to 2023). A primary or metastatic malignant neoplasm that affects the colon or rectum. "Of note, a previous study found GATA5 hypermethylation and associated epigenetic silencing to be involved in carcinogenesis of gastric and colorectal cancers." (PMID 24533449, 2014). "In vitro studies have shown that GATA4 and GATA5 have a tumor- inhibitory effect in colorectal cancer cells." (PMID 36961416, 2023). "The DNA methylation of GATA4 and GATA5 is a common and specific event in colorectal cancer." (PMID 36961416, 2023). "The level of GATA5 protein in colorectal cancer tissues is clearly lower than in normal tissues due to DNA promoter methylation; in contrast, overexpression of GATA5 significantly inhibits the progression of colorectal cancer cells." (PMID 35565203, 2022).